OLR1 (oxidized low density lipoprotein receptor 1)
Description:
Receptor that mediates the recognition, internalization and degradation of oxidatively modified low density lipoprotein (oxLDL) by vascular endothelial cells. OxLDL is a marker of atherosclerosis that induces vascular endothelial cell activation and dysfunction, resulting in pro-inflammatory responses, pro-oxidative conditions and apoptosis. Its association with oxLDL induces the activation of NF-kappa-B through an increased production of intracellular reactive oxygen and a variety of pro-atherogenic cellular responses including a reduction of nitric oxide (NO) release, monocyte adhesion and apoptosis. In addition to binding oxLDL, it acts as a receptor for the HSP70 protein involved in antigen cross-presentation to naive T-cells in dendritic cells, thereby participating in cell-mediated antigen cross-presentation. Also involved in inflammatory process, by acting as a leukocyte-adhesion molecule at the vascular interface in endotoxin-induced inflammation. Also acts as a receptor for advanced glycation end (AGE) products, activated platelets, monocytes, apoptotic cells and both Gram-negative and Gram-positive bacteria. (Microbial infection) May serve as a receptor for adhesin A variant 3 (nadA) of N.meningitidis.
Synonyms: LOX-1; CLEC8A; LOX1; SCARE1; LOXIN; SLOX1
Tractability: Small molecule: a structure with a bound ligand is known. Antibody: its Gene Ontology location is reachable by antibodies, with high confidence; UniProt places it where antibodies can reach, with medium confidence; UniProt predicts a signal peptide or a membrane-spanning region. PROTAC: ubiquitination databases record sites on it.
Chemical probes: BI-0115 (high quality)
Gene: Protein-coding gene on chromosome 12 (10,158,301 to 10,172,138, reverse strand). Ensembl gene ENSG00000173391.
Subcellular location: Cell membrane; Membrane raft; Secreted
Subcellular location (Human Protein Atlas): Nucleoplasm; Plasma membrane; Vesicles
Pathways (Reactome):
Hemostasis: Cell surface interactions at the vascular wall
Immune System: Neutrophil degranulation
Gene Ontology:
Molecular function: identical protein binding; protein binding; low-density lipoprotein particle receptor activity
Biological process: blood circulation; leukocyte cell-cell adhesion; lipoprotein metabolic process; proteolysis; vesicle-mediated transport
Cellular component: plasma membrane; receptor complex; membrane; specific granule membrane; tertiary granule membrane; extracellular region; membrane raft
Genetic constraint (gnomAD): Loss-of-function variants: 21 observed, 28.71 expected, observed/expected ratio (o/e) 0.73, 90% interval 0.52 to 1.05. The upper end of that interval is the gene's LOEUF score, 1.05, which puts it in group 4 of 6, group 1 being the genes least tolerant of losing a copy. Missense variants: 248 observed, 295.88 expected, observed/expected ratio (o/e) 0.84, 90% interval 0.75 to 0.93. Synonymous variants: 107 observed, 110.94 expected, observed/expected ratio (o/e) 0.96, 90% interval 0.82 to 1.13.
Homologues: Orthologues: chimpanzee OLR1 (99% identical), macaque OLR1 (95% identical), dog OLR1 (74% identical), rabbit OLR1 (71% identical), pig OLR1 (70% identical), rat Olr1 (67% identical), guinea pig OLR1 (64% identical), mouse Olr1 (60% identical), zebrafish si:ch211-170d8.8 (16% identical), zebrafish si:ch211-193e13.5 (15% identical), Drosophila melanogaster rgn (14% identical), zebrafish si:dkey-26c10.5 (14% identical), and 2 more. Paralogues in human: CLEC7A (29% identical), CLEC12B (25% identical), CLEC9A (25% identical), CLEC1A (23% identical), CLEC12A (23% identical), KLRK1 (22% identical), KLRG1 (19% identical), CLEC1B (19% identical), KLRD1 (18% identical), KLRB1 (17% identical), KLRG2 (16% identical), KLRC1 (16% identical), and 11 more.
Diseases named in the same sentence as OLR1 in open-access papers:
OLR1 is named in the same sentence as 213 diseases in open-access papers, as found by Europe PMC text mining. Sharing a sentence is not in itself a finding about the gene and the disease. The quoted sentences say what the papers report.
atherosclerosis (274 papers, 2007 to 2026). A disease characterized by the build-up of fatty material and calcium deposition in the arterial wall resulting in partial or complete occlusion of the arterial lumen. "We also observed increased expression of the potent vasoactive peptide endothelin-1 (EDN1) as well as oxidized low-density lipoprotein receptor-1 (OLR1), which is a key molecule associated with endothelial dysfunction during atherosclerosis progression." (PMID 37845224, 2023). "Taken together, these findings suggest that glucocorticoids (such as DEX) most likely modify the risk of atherosclerosis conferred by the cis-regulatory variation of OLR1." (PMID 37007953, 2023). "Meta-analysis showed that OLR1 is associated with atherosclerosis and contributes to the susceptibility risk of ischemic stroke." (PMID 36969251, 2023). "LOX-1 encoded by the OLR1 gene is involved in the pathogenesis of atherosclerosis, and activation of LOX-1 is an important mechanism leading to plaque instability and progression to acute coronary syndrome." (PMID 35909123, 2022). "In conclusion, OLR1 holds promise as a novel diagnostic and therapeutic target for atherosclerosis and CHD." (PMID 35795669, 2022). "Previous studies have demonstrated that OLR1 mediates vascular endothelial cell damage and atherosclerosis and the enhancement of vascular permeability caused by oxidized LDL12,13." (PMID 34344944, 2021). "The up‐regulation of lectin‐like oxidized low‐density lipoprotein receptor‐1 (LOX‐1), encoded by the OLR1 gene, plays a fundamental role in the pathogenesis of atherosclerosis." (PMID 26542080, 2016). "Like other scavenger receptors implicated in the atherosclerosis, the OLR1 mediated the OxLDL-induced NF-κB activation in VSMCs, which in turn augmented the ICAM-dependent monocyte adhesion onto the activated VSMCs." (PMID 26305474, 2015). "Ox-LDL acts by binding to several SRs, including SR-A, SR-BI, CD36, and lectin-like oxidized low-density lipoprotein receptor-1 (LOX-1) and transforms macrophages to foam cells, which are a hallmark of atherosclerosis." (PMID 26697490, 2015). "Altered expression and function of lectin-like oxidized low-density lipoprotein receptor-1 (LOX-1) has been associated with several diseases such as endothelial dysfunction, atherosclerosis and obesity." (PMID 25170920, 2014). "The lectin-like oxidised LDL receptor-1 (OLR1) gene encodes a scavenger receptor implicated in the pathogenesis of atherosclerosis." (PMID 22347434, 2012). "Notably, in recurrent psoriasis-like conditions, we observed an increase in the expression of Olr1, a gene associated with atherosclerosis." (PMID 40599782, 2025). "Lectin-like oxidized low-density lipoprotein receptor 1 (LOX-1) is physiologically expressed in low amounts on endothelial cells, and sits upstream of several matrix metalloproteinases and pro-inflammatory pathways implicated in atherosclerosis." (PMID 35722087, 2022). "However, only Metf and A-76 group identified DEGs directly associated with atherosclerosis (only two gene were involved, including Tnfsf4 and Olr1)." (PMID 28178661, 2017). "Finally, since OLR1 is a relevant factor in the development of atherosclerotic lesions, this strong upregulation during T. cruzi infection can explain, at least in part, the major susceptibility to atherosclerosis in T. cruzi infected mice." (PMID 24812617, 2014). "Lectin-like oxidized low-density lipoprotein receptor-1 is known to be involved in the development of osteoarthritis and atherosclerosis." (PMID 40011998, 2025). "Increased pathways involved in lipids and atherosclerosis likely relate to the formation of foam cells (e.g. genes Olr1, Abca1, and Abcg1)." (PMID 40513100, 2025). "Endothelial overexpression of OLR-1 also increases plaque formation and promotes atherosclerosis in vivo by promoting oxLDL uptake and internalization." (PMID 38280036, 2024).
atherosclerosis (continued). "In atherosclerosis, miR‐485‐3p targets Olr1 to regulate vascular inflammation and lipid transport, thereby participating in the development of the disease." (PMID 39010253, 2024). "Lectin-like oxidized low-density lipoprotein receptor-1 (LOX-1) is a well-known receptor for ox-LDL that plays a vital role in atherosclerosis." (PMID 36768748, 2023). "Lectin-like oxidized low-density lipoprotein receptor-1 (LOX-1) is thought to be a biomarker of several diseases, including vascular inflammation and atherosclerosis." (PMID 36776908, 2023). "Ox-LDLs, as an important atherosclerosis contributor, were mainly up taken by ECs through binding with lectin-like oxidized low-density lipoprotein receptor-1 (LOX-1), mediating immune reactions and participating in the pathogenesis of atherosclerosis." (PMID 37371838, 2023). "In recent years, OLR1 research has mainly focused on cardiovascular and metabolic diseases, such as atherosclerosis and diabetes." (PMID 36452079, 2022). "The important physiological roles of OLR1 have already been demonstrated in platelet activation, endothelial dysfunction, leukocyte migration, plaque formation, and atherosclerosis as a consequence of these pathological events." (PMID 34344944, 2021). "OLR1 is a metabolic gene that encodes for the Lectin-like oxidized low-density lipoprotein receptor-1 (LOX-1), implicated in inflammation, atherosclerosis, ROS, and metabolic disorder-associated carcinogenesis." (PMID 34439368, 2021). "Several inflammatory and atherosclerosis-related stimuli have been shown to induce OLR1 expression, including lipopolysaccharide (LPS), TNFα, interleukin-1 (IL-1), interferon gamma (IFNγ), oxLDL, and angiotensin II." (PMID 34867460, 2021). "In the context of acute coronary syndrome as a result of the progression of atherosclerosis, OLR1 has been thought to be involved in prothrombotic pathways induced by oxidized LDL21." (PMID 34344944, 2021). "PCSK9 inhibition decreases the ROS production in endothelial cells and smooth muscle cells by inhibiting lectin-like oxidized low-density lipoprotein receptor-1 (LOX-1) expression in mice atherosclerosis models." (PMID 33348578, 2020). "Trib1 controls atherosclerotic plaque macrophage function by up-regulating OLR1, promoting foam cell formation and atherosclerosis." (PMID 31692955, 2019). "Lectin-like oxidized low-density lipoprotein receptor-1 (LOX-1) is involved in the pathophysiology of atherosclerosis and acute coronary syndromes (ACS)." (PMID 30799974, 2019). "Lectin‐like oxidized low‐density lipoprotein receptor‐1 (LOX‐1) is the main ox‐LDL endothelial scavenger receptor (SR) 2 and the ox‐LDL/LOX‐1 interaction contributes to the triggering of endothelial dysfunction characteristic of atherosclerosis development." (PMID 26542080, 2016). "Both OLR1 and PCSK9 genes are associated with atherosclerosis, cardiovascular disease and ischemic stroke." (PMID 26666837, 2015). "Both OLR1 and PCSK9 are positively linked, where the inhibition of PCSK9 can suppress the development of atherosclerosis by disrupting LOX-1 expression." (PMID 26666837, 2015). "The authors of that study noted that multiple genes involved in lipid metabolism, cholesterol biosynthesis and atherosclerosis, including OLR1 (oxidized LDL receptor 1), SCD1, SREBP1, SNAP23 and VAMP4 were deregulated in cell transformation." (PMID 23292678, 2013). "OLR1 is expressed in highly vascularized tissues, plays critical roles in the development of atherosclerosis and related disorders, and is upregulated in hypertensive, dyslipidemic, and diabetic animals and humans." (PMID 24040759, 2013). "Third, Wang and co-workers focused their analysis on the presence of plaque, (advanced atherosclerosis) while we focused on IMT (atherogenesis) thus suggesting a dual role for OLR1 in different phases of the atherogenic process." (PMID 22347434, 2012).
atherosclerosis (continued). "In apolipoprotein E (ApoE)−/− atherosclerosis models, 8-week oral F1 treatment at 50 mg/kg/day induced remarkable reduction in atherosclerotic lesion area and decreased lectin-like oxidized low-density lipoprotein receptor-1 (LOX-1) and TLR4 expression." (PMID 41155644, 2025). "The oxidized low-density lipoprotein receptor 1 (OLR1) also known as lectin-type oxidized low-density lipoprotein receptor-1 (LOX-1) is a type II membrane glycoprotein receptor that plays an important role in atherosclerosis." (PMID 39905294, 2025). "LOX-1 is a scavenger receptor for oxidized low density lipoprotein receptor 1 (ox-LDL) which plays an important role in the development of atherosclerosis, we analyzed the plasma levels of ox-LDL and found it to be significantly higher in plasma of CCM patients vs. controls." (PMID 39234183, 2024). "Similarly, fisetin reduced the buildup of lipids in the plaque that causes atherosclerosis by decreasing the activity of proprotein convertase subtilisin/kexin type 9 (PCSK9) and lectin-like oxidized low-density lipoprotein receptor-1 (LOX-1)." (PMID 37174317, 2023). "Also, an increased gene expression of oxidized low-density lipoprotein (LDL) receptor-1 (Olr1), a key molecule in endothelial dysfunction in the progression of atherosclerosis, was detected in the aorta of infected mice." (PMID 34344944, 2021). "OLR1 is among the genes that make up this signature, which indicates a more significant involvement of metabolism and neoplastic transformation and suggests molecular links between atherosclerosis and cancer." (PMID 28146073, 2017). "Our findings suggest that the rs1050286 SNP in the OLR1 3′UTR, by disrupting the regulatory role of miR‐24 on OLR1 expression, may contribute to the occurrence of atherosclerosis." (PMID 26542080, 2016). "Thus, this study elicits the protein network organizing the phenotypic change of VSMC in the vascular injury diseases such as atherosclerosis and discovers OLR1 as a novel molecular link between the proliferative and inflammatory responses of VSMCs." (PMID 26305474, 2015). "In addition, the OLR1 gene in the NKC is polymorphic and polymorphisms of this gene have been associated with atherosclerosis, myocardial infarction, and Alzheimer's disease." (PMID 21305040, 2011). "Also, P. gingivalis triggered the expression of lectin-like oxidized low-density lipoprotein receptor-1 (LOX-1) in both endothelial cells and monocytes, with LOX-1 known to contribute to atherosclerosis by inducing endothelial inflammation and monocyte-endothelial interaction." (PMID 39717783, 2024). "Scavenger receptor class A (SR-A), cluster of differentiation 36 (CD36), and lectin-like oxidized low-density lipoprotein receptor-1 (LOX-1) are upregulated in the atheroma, mediating the uptake of oxLDL, promoting lipid accumulation within the macrophages, and finally exacerbating atherosclerosis." (PMID 35548442, 2022). "A recent study showed that Epac1 could promote foam cell formation and atherosclerosis development by upregulating oxidized low-density lipoprotein receptor 1 (LOX1) via stimulation of protein kinase C (PKC), which is an important step of atherosclerosis development." (PMID 35910387, 2022). "Background and objectives: Lectin-like oxidized low density lipoprotein receptor-1 (LOX-1) has been recognized as the primary receptor for carbamylated low-density lipoproteins (cLDL) and is increasingly being viewed as a critical mediator of vascular inflammation and atherosclerosis." (PMID 31443320, 2019). "Thus, a critical question to consider is whether mTRIB1-induced OLR1 expression serves an (athero-) protective role in human atherosclerosis, for example, by reducing the exposure of plaque-resident vascular cells (where this disease is initiated) to oxLDL." (PMID 31692955, 2019).
atherosclerosis (continued). "Serum OLR-1 levels are positively related to the incidence of CVD, and activation of the receptor is suggested to play a role in atherosclerosis, myocardial fibrosis, and endothelial dysfunction." (PMID 39101637, 2024). "Ox-LDL receptor-1 (OLR-1/LOX-1), tumor necrosis factor alpha (TNF-α), and atherogenic interleukins (IL-1β, IL-6, etc.)play an important role in the pathogenesis of atherosclerosis." (PMID 39770544, 2024). "Endothelial soluble lectin-type oxidized low-density lipoprotein receptor 1 (sLOX-1) recognizes oxidized low-density lipoprotein (LDL) and triggers downstream signaling leading to atherosclerosis." (PMID 38234947, 2023). "Two platelet receptors that are important in the development of atherosclerosis are scavenger receptors, such as the cluster of differentiation 36 (CD36) and lectin-like oxidized low-density lipoprotein receptor 1 (LOX-1)." (PMID 35326219, 2022). "Furthermore, lectin-like oxidized low-density lipoprotein receptor-1 (LOX-1), acting as the main OxLDL in ECs, is reported to overexpressed in atherosclerotic lesions, which is participated in several cellular processes modulating the pathogenesis of atherosclerosis." (PMID 31210063, 2019). "Pathway “Lipid and Atherosclerosis” and related genes, for example, LYN, SELP, OLR1." (PMID 40621499, 2025). "Although this process has been well characterized in the settings of developing atherosclerosis, it has not yet been established what role Olr1 plays in the acute phase after ischemia-reperfusion and in particular in the affected MCAs." (PMID 33297959, 2020). "The interaction between the lectin-like oxidized low-density lipoprotein receptor-1 (LOX-1) and oxidatively modified low-density lipoprotein (ox-LDL) plays a significant role in the pathobiology of atherosclerosis, as well as myocardial ischemia and hypertension." (PMID 26578342, 2015). "OLR1, as a receptor of oxidized LDL, is a marker for atherosclerosis, which could activate pathways involving inflammatory and hypoxia in macrophages and vascular endothelial cells." (PMID 26061746, 2015).